COL4A4 (collagen type IV alpha 4 chain)
Diseases named in the same sentence as COL4A4 in open-access papers (continued):
Sharing a sentence is not in itself a finding about the gene and the disease.
tumor (15 papers, 2012 to 2025). "Previous reports have also indicated differential expression of COL4A4 in other tumors, correlating with prognosis, tumor stemness, immune checkpoint gene expression, and TME parameters." (PMID 39968416, 2025). "Among them, the expression of COL1A1, COL10A1 and COL11A1 was particularly higher, and that of COL4A4, COL6A5 and COL14A1 was especially lower in tumor tissues, indicating their possible roles as diagnostic markers for ESCC." (PMID 31598423, 2019). "The COL4A1 and COL4A2 had the most significant association with tumor grade (AUC = 0.822 and 0.820 in G2 vs G3 and G4; AUC = 0.863 and 0.834 in G3 vs G4), followed by COL4A3 and COL4A4 (AUC = 0.539 and 0.585 in G2 vs G3 and G4; AUC = 0.677 and 0.753 in G3 vs G4)." (PMID 40351420, 2025). "As the tumor progressed, COL4A1, COL4A2 and COL4A6 expression gradually increased, and COL4A3, COL4A4 and COL4A5 gradually decreased." (PMID 40351420, 2025). "Among them, the expression of COL1A1, COL10A1, and COL11A1 were found to be particularly high in tumor tissues compared with normal counterpart; on the contrary, the expression of COL4A4, COL6A5 and COL14A1 was significantly lower in tumor tissues." (PMID 34199373, 2021). "The mRNA expression level of all six type IV collagen genes (COL4A1, COL4A2 COL4A3, COL4A4, COL4A5 and COL4A6) was higher in metastatic tissue compared to primary tumor tissue, although being significant only for COL4A3 (p = 0.013) and COLA4A4 (p = 0.005) genes." (PMID 35693557, 2022). "Therefore, the increased vessel formation in tumors may be associated with the upregulation of COL4A1 and COL4A2 expression, and the aggressiveness of the tumor may result in the downregulation of COL4A3 and COL4A4 expression and minor Col IV degradation to promote invasion of tumors." (PMID 40351420, 2025). "The findings revealed that the mRNA expression of COL4A4 was stably increased in low T and M stage groups as well as in the low WHO grade group, and these results were further validated in the test cohort, implying that COL4A4 might act as an important predictive factor in tumor development." (PMID 34960256, 2021). "In contrast, the variation of COL4A3, COL4A4 and COL4A5 expression between tumor and normal tissues were lacking of significance, and presented an inconsistent tendency in three databases." (PMID 40351420, 2025). "However, we observed that optiCA1 overexpressing tumor cells, when compared with the controls, had not statistically changed expression profile of mRNAs (COL1A1, COL4A4, LAMC2, CTHRC1, and WNT7B)." (PMID 31963697, 2020).
cancer (8 papers, 2019 to 2025). A tumor composed of atypical neoplastic, often pleomorphic cells that invade other tissues. "Interestingly, several genes were known to be regulated by the TGFβ pathway (e.g., BMF, COL4A4) and/or expressed in several cancers (e.g., HOTAIR, MRC2, POSTN, SPARC)." (PMID 34830779, 2021). "As was reported, several hub collagen-related genes including FN1, IL6, COL4A4 and COL7A1 were involved in the progression and development of variable cancers." (PMID 34960256, 2021).
genetic disorder (6 papers, 2021 to 2025). "AS is a rare genetic disorder that caused by pathogenic variants in COL4A3, COL4A4, and COL4A5 that result in abnormalities of the collagen IV α345 network of basement membranes." (PMID 34774011, 2021). "Studies have shown that 15–60% of human genetic diseases are caused by splicing variants, and it has been speculated that the true proportion of splicing variants in COL4A3/COL4A4 may be underestimated." (PMID 35386907, 2022).
autosomal dominant disease (1 paper, 2025). Autosomal dominant form of disease. "It must also be acknowledged that study participants with autosomal dominant disease represented a severe disease subset of the larger group of participants with heterozygous variants in COL4A3 and COL4A4." (PMID 40485716, 2025).
metabolic disorders (1 paper, 2025). "Matrix protein molecules such as Adipoq, Angptl4, Col4a4, Hrg, Tgfbi, Tgm2, Vcan and Vtn increase with age, and they may promote the occurrence of fatty liver during aging by affecting fat accumulation and metabolic disorders." (PMID 40537154, 2025).
COL4A4 also shares sentences with these, for which no sentence is quoted: autosomal dominant Alport syndrome (17 papers); autosomal recessive Alport syndrome (16); X-linked Alport syndrome (10); Fabry disease (4); glomerulopathy (3); hereditary nephritis (3); nail-patella syndrome (3); sensorineural hearing loss (3); Basement membrane disease (2); dilated cardiomyopathy (2); glomerulosclerosis (2); Hearing impairment (2); membrane nephropathy (2); Alzheimer disease (1); aneurysm (1); aniridia (1); Areflexia (1); auditory neuropathy spectrum disorder (1); autoimmune disease (1); cataract (1); cerebellar ataxia (1); colon carcinoma (1); essential hypertension (1); Friedreich ataxia (1); genetic renal diseases (1); glaucoma (1); hypertensive nephropathy (1); hypertrophic cardiomyopathy (1); intracranial aneurysms (1); Leber congenital amaurosis (1).
A further 24 diseases each share a sentence with COL4A4 in 1 paper.